CASP1 (caspase 1)
Diseases named in the same sentence as CASP1 in open-access papers (continued):
Sharing a sentence is not in itself a finding about the gene and the disease.
tumor (continued). "Here, our finding showed that DPP-4i promoted caspase-1-dependent processing of IL-1β and IL-33 by activating NF-кB–NLRP3 activation, indicating that DPP-4i may reprogram tumor microenvironment by promoting 4T1 cells-derived IL-1β and IL-33 via NF-кB–NLRP3 pathway." (PMID 34631556, 2021). "Therefore, the MEG3/NLRP3/caspase-1/GSDMD pathway may be one of the important mechanisms for DDP to induce pyroptosis and exert anti-tumor effects in TNBC." (PMID 34326697, 2021). "In contrast, cluster of differentiation 38 (CD38) has been demonstrated to act as a tumor suppressor gene in HNSCC, triggering pyroptotic cell death by activating NLRP3 and caspase-1; thus, by inhibiting CD38 expression, HNSCC cells might be able to escape NLRP3 inflammasome-mediated pyroptosis." (PMID 34064909, 2021). "Tumor cell suspensions from WT or Caspase-1 KO mice were incubated with a combination of IL-12+IL-18 cytokines, or with crosslinking antibodies against activating receptors (NKp46, Ly49D, NKG2D) or with different tumor cell lines (4T1, and YAC1 cells, a classical NK cell target)." (PMID 33042810, 2020). "The fact that we observed caspase-8 activity but no caspase-1 induction in KC following PH in animals without tumor might hint toward an analogous regulation in KC." (PMID 33178579, 2020). "Notably, the activation of NLRP3/caspase-1 signaling induces apoptosis rather than pyroptosis in tumor cells lacking GSDMD." (PMID 31501419, 2019). "In addition, our western blot results showed that NLRP3, Caspase-1, IL-18 and IL-1β were highly expressed in the Tgfbr1/Pten 2cKO mice SCCHN tumor lysates compared with control wild type tongues, and the expression of BMI1, ALDH1 and CD44 were consistent with NLRP3 inflammasome." (PMID 28865486, 2017). "Given that blockade of NLRP3 inflammasome could delay tumorigenesis in SCCHN mice by reducing the production of IL-1β, and the stimulation on NLRP3 inflammasome from early tumor is less than advanced tumor, which might account for the decreased expression of NLRP3 and pro-Caspase-1." (PMID 28865486, 2017). "Notably, caspase-1 inhibition did not affect the overall intestinal tumour load or size in unimmunized hCEA-Tg/ApcMin/+ or ApcMin/+ mice." (PMID 28397782, 2017). "The tumor cells that silenced ASC were not able to secrete IL-1 or cleave caspase-1." (PMID 27768771, 2016). "Casp1/11−/− DIO mice had significantly reduced tumour growth compared with WT DIO mice, but CASP1/11 deficiency had no impact on tumour growth in normal-weight mice, suggesting that simply gaining body weight in the Casp1/11−/− mice is no longer sufficient for tumour growth." (PMID 27708283, 2016). "We observed that T0901317 activated caspase-1 in tumor samples but not in healthy tissues." (PMID 26450852, 2015). "In the caspase family, caspase-1, caspase-3, caspase-6, and caspase-9 are major cascade activation proteins, and PDT initiates the apoptosis cascade reaction primarily by activating caspase-dependent intrinsic and extrinsic pathways; this cleaves PARP, ultimately leading to apoptosis of tumor cells." (PMID 24204937, 2013). "Interestingly, HLA-induced tumor necrotic regions did not express cleaved Caspase-1." (PMID 38191648, 2024). "Thus, non-selective administration of caspase-1 inhibitors may promote tumor growth, while selective caspase-1 inhibition in MDSCs may attenuate tumor development." (PMID 36932407, 2023). "We hypothesized that caspase-1- dependent secretomic transcripts and caspase-4-dependent secretomic transcripts are modulated in Treg from normal tissues, non-malignant disease Treg, and Treg from tumor spleens and tumors." (PMID 34084175, 2021). "However, unlike normal colonic epithelial cells they derive from, a variable proportion of tumor cells per tumor exhibits an aberrantly activated inflammasome (expression of active caspase-1 and release of mature IL-18), irrespective of the microsatellite status." (PMID 33430344, 2021).
tumor (continued). "Cleaved caspase 1 (p20) (P < 0.05), cleaved caspase 3 (p17, 19) (P < 0.01), cleaved caspase 8 (p18, 43) (P < 0.05), cleaved caspase 9 (p37, 39) (P < 0.05), and TNF-stimulated gene 6 protein (TSG6) (P < 0.05) could be significantly identified in Sal-YB1-treated tumor mass by Western blotting." (PMID 26286454, 2015). "Meanwhile, the mRNA and protein expression levels of NLRP3, caspase 1, GSDMD, IL-1β and IL-18 in H(FMT) group were higher than that in T(FMT) group, while there were no noticeable difference between T(FMT) group and tumor model group." (PMID 40046008, 2024). "The most active compound (7c) against all the tumour cell lines studied (IC50 0.42–0.86 μM) does not produce any modification in the expression of pro-caspase 3, but increases the caspase 1 expression, and promotes pyroptosis." (PMID 34251942, 2021). "More analytically, they showed that HS is able to dampen caspase-1 activation without affecting 5-FU-induced MDSC death, which results in the promotion of antitumor immunity and the inhibition of tumor growth." (PMID 34441758, 2021). "PYCARD, CASP-1, and NLRP3 protect against against tumorigenesis as shown in studies that demonstrated increased tumor growth in mice lacking NLRP3 inflammasome components." (PMID 33014808, 2020). "This indicates that caspase-1 or its final product, IL-1β, is not crucial for HNSCC cell survival in isolated conditions without a surrounding tumor microenvironment." (PMID 28430665, 2017). "To examine whether CASP1 modulates ODBP in NLRP3 inflammasome-dependent manner, we obtained Nlrp3−/− mice and found that, while the mice lacking NLRP3 had less weight gain with HFD than WT mice, NLRP3 deficiency had no significant impact on tumour growth in DIO or normal-weight mice." (PMID 27708283, 2016). "We, therefore, investigated whether targeting other members of the IL-1 pathway (Caspase-1, IL1β or IRAK1) could reduce bone metastases without increasing tumour growth outside of the bone." (PMID 36230739, 2022). "Moreover, the expression of caspase-1, IL-1β, and GSDMD was negative correlation with increasing tumor grade, clinical stage, and poor clinical prognosis in BC, indicating pyroptosis played a central role in BC tumorigenesis and progression." (PMID 35464869, 2022). "Our results suggest that doxycycline has an inhibiting effect on LPS priming of the inflammasome, and that it can attenuate the production of pro-CASP1 and NLRP3 RNA and NLRP3 protein assembly irrespective of the level of IL-1β production and secretion in these tumor cells." (PMID 34577552, 2021). "A possible explanation for the lack of increased NLRP3 expression, despite elevated caspase-1, IL1β and IL18, is that only specific locations have cells with activated NLRP3 (i.e., a cluster of invading immune cells at the tumor/tissue interface) and tissue was from regions without altered NLRP3." (PMID 31923221, 2020). "In our current research, both caspase-1 inhibitors do not display significant inhibitory effects on TAM’s cell viability or growth, but leads to the disruption of PPARγ/MCAD activity and repolarization/reprogramming of TAMs, eventually suppressing the tumor growth." (PMID 28974683, 2017).
cancer (185 papers, 1999 to 2026). A tumor composed of atypical neoplastic, often pleomorphic cells that invade other tissues. "According to a study analyzing the caspase-1, -4, and -5 gene mutations in cancers, it is indicated that inhibition of caspase-5 probably contributes to carcinogenesis in microsatellite instability-positive tumor entities." (PMID 35198448, 2022). "Inflammatory caspases have also been linked to cancer, where especially caspase-1 and inflammasome activation can lead to inflammation-driven cancer development and progression." (PMID 33802262, 2021). "For cancer cells, loss of caspase-1 gene expression was observed in human prostate cancer and human hepatocellular carcinoma." (PMID 29440460, 2018). "Our results show that treatment of A549 cancer cells with 4-HBA induces the transcription of (amongst others) caspase-1, IL1β, and IL18 encoding genes." (PMID 29352134, 2018). "To Further confirm the detrimental role of TAM-intrinsic caspase-1 in vivo, EO771 cancer cells were implanted in the flank of nude mice alone or in combination with WT or caspase-1-deficient (KO) BMDMs derived from caspase-1−/− mice." (PMID 28974683, 2017). "Studies on the expression of ASC (apoptosis-associated speck-like protein containing a CARD) and caspase-1 with reference to inflammasome in cancer are limited." (PMID 28663562, 2017). "The expression of CASP1 is either positively or negatively associated with distinctive pathways in cancer." (PMID 28383547, 2017). "Pyroptosis is a newly discovered way of programmed cell death, and it is associated with activation of caspase-1 to induce cancer cell death." (PMID 27705930, 2016). "While caspase-1 or -2-deficiency has been associated with increased susceptibility to tumor induction, deficiency of caspase-3 has been linked inversely to a decreased incidence of cancer." (PMID 38824481, 2024). "In addition, assembled inflammasomes can activate caspase-1 and cause IL-1β to be secreted from cancer cells." (PMID 32577124, 2020). "First, we compared the expression of NLRP3 (and IL‐1β and CASP‐1) in our PTCC data set with other cancer types to demonstrate that blood cancers generally express more NLRP3 (and IL‐1β and CASP‐1)." (PMID 40104043, 2025). "Recent advances have highlighted the potential of targeting inflammasome components such as sensor proteins (e.g., NLRP3, AIM2), adaptor proteins (e.g., ASC), caspase-1, and downstream cytokines IL-1β and IL-18—to modulate the immune response against cancer." (PMID 40155968, 2025). "In A549 cancer cells, the conditioned medium from NK-92 cells caused the phosphorylation of STAT1 at Tyr701, as well as the upregulation of the IRF1 and CASP1 proteins, which is consistent with the activity of IFNγ." (PMID 40512405, 2025). "Berberine is a promising drug for cancer therapy that upregulates caspase-1 mRNA and protein expression in an HCC cell line (HepG2 cells) in a concentration-dependent manner, inhibiting cell survival via caspase-1-mediated pyroptosis." (PMID 39917567, 2025). "NLRP3/caspase-1/GSDMD-mediated pyroptosis is emerging as a promising therapeutic target in cancer treatment, thereby leading to the search for effective drugs and biomarkers for cancer treatment." (PMID 38265972, 2024). "Researchers also detected an increased level of gasdermin D N-terminal domain (GSDMD-N) and cleaved caspase-1 within the cancer cells, suggesting the existence of the caspase-1/GSDMD pathway of pyroptosis." (PMID 39398428, 2024). "For effective clinical translation, improved drug design together with a deeper understanding of caspase-1 function in normal tissues is needed before this class of therapeutics can be considered for cancer treatment." (PMID 39353903, 2024).
cancer (continued). "For example, combined with ruthenium (II) polypyridyl complex Δ-Ru1, taxol improved caspase-1/GSDMD induced pyroptosis in Taxol-resistant cancer cells." (PMID 39300122, 2024). "Inflammasome-mediated caspase-1 activation plays a crucial role in regulating the expression of pro-inflammatory genes or apoptotic pathways, making caspase-1 an essential factor in the pathogenesis and treatment of various diseases, including cancer." (PMID 38990306, 2024). "Our previous studies revealed that VX765, a caspase-1 inhibitor, increases the secretion of pro-angiogenic cytokines from cancer cells." (PMID 38543085, 2024). "In a study using near infrared (NIR) nanomicelles with combined PDT and PTT characteristics for cancer treatment, caspase-1/GSDMD-dependent pyroptosis was also identified in the treatment process." (PMID 39398428, 2024). "This study examines the anti-cancer effects of usenamine A in LUAD and identifies the underlying mechanism involving the activation of NLRP3/caspase-1/GSDMD-mediated pyroptosis." (PMID 38265972, 2024). "In most of the cancer cell lines analyzed, including cell lines reported to carry NLRP3 mutations, the NLRP3 protein was barely detectable, whereas ASC or caspase-1 was variably expressed." (PMID 36746533, 2023). "STING and CASP1 were mainly detected in the cell cytoplasm and can be observed in cancer cells and surrounding stroma." (PMID 35957613, 2023). "The observed decreases in these BMs with anthracycline exposure suggest that some patients with cancer have elevated MPO and CASP-1 levels at baseline because of the systemic inflammation related to cancer." (PMID 37106424, 2023). "While caspase-1 was significantly upregulated in immune-stromal cells of cancer tissues than that of normal tissues." (PMID 38031068, 2023). "Evidence shows that the induction of pyroptosis via inflammasome/caspase-1 signalling stimulates a series of inflammatory cascades by releasing inflammatory mediators, which are strongly pertinent to tumorigenesis and cancer development." (PMID 35379783, 2022). "Our data corroborate Az-mediated activation of caspase in cancer cells as we showed that LPS-Az induced the expression of CASP1 RNA as compared to LPS-only." (PMID 36012769, 2022). "Remarkably, normal cells treated with a caspase-1 inhibitor showed the de novo accumulation of acidic isoforms similar to those previously found in cancer cells (lanes 5)." (PMID 35256749, 2022). "After that, caspase-1 is activated showing very specific staining in the subset of cancer cells undergoing cell death, which increased 6-fold the number of stained cells as compared to buffer-treated tumors." (PMID 35532120, 2022). "It mainly recruits and activates caspase-1, participates in the process of cell inflammation and pyroptosis, and plays an important role in inflammatory diseases and a variety of cancers." (PMID 35299842, 2022). "Another important player in inflammation is caspase-1, which has been shown to have both tumorigenic and antitumorigenic effects on cancer development and progression, depending on the type of inflammasome and cancer type." (PMID 35883451, 2022). "The NF-κB signaling pathway regulates NLRP3 and caspase-1 in the proliferation and migration of various cancer cells." (PMID 34239588, 2021). "Intriguingly, Flt3L mRNA correlated to the markers of a metagene signature indicative of immunogenic cancer cell death, which encompassed Caspase1 (CASP1), Perforin 1 (PRF1) and Chemokine receptor CXCR3 (CXCR3)." (PMID 34503273, 2021). "CASP1, a key component of the inflammasome, had been reported to have a profound impact on tumors formation and progression in multiple human cancers." (PMID 33999861, 2021). "On the other hand, knockdown of NLRP3 expression inhibited the growth of cancer cells and reduced caspase-1 activation and IL1β maturation." (PMID 34064909, 2021).
cancer (continued). "PRKACA has also been studied in the context of cancer, where its aberrant regulation and overexpression have been related to inflammatory activation of Caspase 1, oncogene activation, and elevated PGE2 levels." (PMID 34877506, 2021). "We performed a retrieval of CASP1 mRNA expression levels in a variety of cancers by using the GEPIA database." (PMID 33999861, 2021). "Methylene Blue, a broad-spectrum inflammasome inhibitor 65, and CASP1 siRNAs were used to suppress inflammasome signaling activation, reflected by decreased IL-1β expression, in cancer cells." (PMID 34815793, 2021). "Animal and cell culture studies showed that arsenic trioxide and other arsenic compounds inhibited NLRP3 inflammasome, caspase-1, and IL-1β inflammatory signaling, and played a major role in its anti-cancer effects." (PMID 32313131, 2020). "And anthocyanin can kill cancer cells and inhibit the migration and invasion abilities of these cells by inducing pyroptosis, which can be suppressed by caspase-1 inhibitors." (PMID 33665167, 2020). "Mechanistic studies have revealed that DHA can inhibit the growth of breast cancer cells and kill cancer cells by increasing caspase-1, activating GSDMD, promoting the secretion of IL-1β, translocating HMGB1 towards the cytoplasm, and forming membrane pore." (PMID 33665167, 2020). "In the present study, we determined that BRD4 was upregulated whereas caspase-1 were downregulated in RCC cancer samples and cell lines." (PMID 32303673, 2020). "As is known to us, pyroptosis is an inflammatory form of caspase-1-dependent programmed cell death that plays an important role in cancer." (PMID 31941010, 2020). "Huaier extract, a type of fungus from Trametes robiniophila, has shown its anti-cancer ability in non-small-cell lung cancer through caspase-1/GSDMD-dependent pyroptosis in vitro and in vivo." (PMID 33665167, 2020). "Altogether, these results indicate that flagellin inhibited caspase-1 activity and production of ROS, and increased necrosis in C26 cancer cells." (PMID 31731747, 2019). "Homozygous deletion of Nlrp1b was found in 75% of mice studied, whereas in humans NLRP1 or its downstream target CASP1 is deleted in 9% of cancers analyzed." (PMID 31780749, 2019). "The chromosome 9 QTL interval contains several genes involved in inflammation and/or in cancer such as Caspase 1 (Casp1) and pannexin 1 (Panx1), involved in the release of mature inflammatory IL-1β." (PMID 31049358, 2019). "Conversely, in the IL-18 deficient AOM/DSS murine model the cancer burden increased mirroring NLRP3 and caspase-1 deficient mice." (PMID 30447690, 2018). "Among the genes in the cancer cells, CASP-1 was downregulated in the HER2-60 brain metastasis more than 21 times than in the HER2-90 brain metastasis." (PMID 30042341, 2018). "Mice models with NLRP3, caspase-1 and ASC adaptor deficiencies show protection against cancer progression." (PMID 30447690, 2018). "Active caspase-1 p20 was detected in every HNSCC cancer tissue sample, suggesting that IL-1β also has to be cleaved to become activated." (PMID 28430665, 2017). "As for cancer, activation of caspase-1 can increase the secretion of pro-inflammatory cytokines to exert carcinogenesis effects or induce cell death to exert carcinostasis effect." (PMID 27705930, 2016). "The activated AIM2 inflammasome in macrophages promotes the proteolytic cleavage and secretion of pro-inflammatory cytokines (IL-1β and IL-18) through the activation of caspase-1, leading to cell senescence, apoptosis and preventing cancer progression." (PMID 27806724, 2016). "Pyroptosis is a caspase-1 dependent programmed cell death, which is involved in the pathologic process of several kinds of cancers." (PMID 27705930, 2016). "While dying cancer cells ultimately manifest cleavage of both caspases, activation of caspase-1 appears to precede that of caspase-3, potentially favoring the necrotic/pyroptotic mechanism of killing." (PMID 26552848, 2015).